LRRN4 (leucine rich repeat neuronal 4)
Description:
May play an important role in hippocampus-dependent long-lasting memory.
Synonyms: NLRR-4; C20orf75; dJ1056H1.1; NLRR4
Tractability: Antibody: UniProt predicts a signal peptide or a membrane-spanning region; its Gene Ontology location is reachable by antibodies, with medium confidence.
Gene: Protein-coding gene on chromosome 20 (6,037,376 to 6,060,313, reverse strand). Ensembl gene ENSG00000125872.
Subcellular location: Membrane
Subcellular location (Human Protein Atlas): Mitotic chromosome; Nucleoli; Nucleoli rim
Gene Ontology:
Molecular function: protein binding
Biological process: long-term memory
Cellular component: extracellular exosome; plasma membrane; membrane
Genetic constraint (gnomAD): Loss-of-function variants: 26 observed, 16.46 expected, observed/expected ratio (o/e) 1.58, 90% interval 1.14 to 1.93. The upper end of that interval is the gene's LOEUF score, 1.93, which puts it in group 6 of 6, group 1 being the genes least tolerant of losing a copy. Missense variants: 1,070 observed, 914.81 expected, observed/expected ratio (o/e) 1.17, 90% interval 1.11 to 1.23. Synonymous variants: 496 observed, 429.62 expected, observed/expected ratio (o/e) 1.15, 90% interval 1.07 to 1.24.
Homologues: Orthologues: chimpanzee LRRN4 (98% identical), macaque LRRN4 (93% identical), rabbit LRRN4 (65% identical), mouse Lrrn4 (64% identical), guinea pig LRRN4 (64% identical), rat Lrrn4 (62% identical), tropical clawed frog lrrn4 (35% identical). Paralogues in human: ISLR2 (12% identical), LRRN4CL (11% identical), ISLR (11% identical).
Diseases named in the same sentence as LRRN4 in open-access papers:
LRRN4 is named in the same sentence as 17 diseases in open-access papers, as found by Europe PMC text mining. Sharing a sentence is not in itself a finding about the gene and the disease. The quoted sentences say what the papers report.
mesothelioma (3 papers, 2011 to 2025). A usually malignant and aggressive neoplasm of the mesothelium which is often associated with exposure to asbestos. "The observation that LRRN4 is highly expressed in the primary mesothelial cells, is lost in 8 of the mesothelioma cell lines and is expressed at lower levels in the remaining 8 lines is of interest." (PMID 21984916, 2011). "Despite this, testing the cell line panel revealed that MSLN still appears to be a better marker of mesothelioma than LRRN4 and UPK3B." (PMID 21984916, 2011). "With this in mind we are currently exploring the development of LRRN4 ELISA based assays for detection of mesothelioma antigens in patient body fluids." (PMID 21984916, 2011). "LRRN4 has been shown to promote colorectal cancer malignancy through activation of the RAS/MAPK pathway, while LRRN3 has been associated with a lower risk of mesothelioma." (PMID 41458604, 2025). "Interestingly MSLN levels appear to be upregulated in the mesothelioma lines compared to the primary mesothelial cells, while LRRN4 and UPK3B, are either lost or down-regulated." (PMID 21984916, 2011). "LRRN4 however has not been previously associated with mesothelioma or the mesothelial lineage." (PMID 21984916, 2011). "Although LRRN4 has not been associated with mesothelioma it has been shown previously to be regulated in response to acute lung injury and in Chronic Obstructive Pulmonary Disease (COPD) suggesting it may play a role in response to lung damage." (PMID 21984916, 2011). "Although a few reports have demonstrated the differential expression of LRRN4 in primary mesothelioma and CRC patients, the functions of LRRN4 in malignant cells are unclear." (PMID 35440048, 2022). "We go on to demonstrate that polyclonal antibodies against two of these, LRRN4 and UPK3B react with human mesothelioma tissue localised to the plasma membrane." (PMID 21984916, 2011). "To confirm the specificity of these markers in human mesothelium and mesothelioma we designed primers against human MSLN, UPK3B, NKAIN4 and LRRN4 and tested their specificity by qRTPCR against a panel of 45 human total RNAs." (PMID 21984916, 2011). "LRRN4 has been identified as a marker of primary mesothelial cells, while it was found to be either nondetectable or downregulated in mesothelioma." (PMID 35440048, 2022).
breast carcinoma (1 paper, 2025). "Among other family members, LRRN3, LRRN4, and LRRN4CL were uniformly downregulated in breast cancer tissues." (PMID 41458604, 2025). "Interestingly, LRRN4 expression did not demonstrate significant differential expression in breast cancer." (PMID 41458604, 2025).
colon cancer (1 paper, 2021). "The results suggested that the relative mRNA expression of LRRN4 (P value <0.001) was high in colon cancer cell lines, which was consistent with the analysis of IHC." (PMID 34919118, 2021).
dilated cardiomyopathy (1 paper, 2021). Cardiomyopathy which is characterized by dilation and contractile dysfunction of the left and right ventricles. "A recent study revealed that the aberrantly low expression of LRRN4 was closely associated with the dilated cardiomyopathy, which reminded us that aberrant LRRN4 expression might also play a role in other diseases." (PMID 34919118, 2021). "For instance, a recent study reported that the aberrantly low expression of LRRN4 was closely associated with the dilated cardiomyopathy, which reminded us that aberrant LRRN4 expression might also play a role in other diseases." (PMID 34919118, 2021).
gastric cancer (1 paper, 2022). A primary or metastatic malignant neoplasm involving the stomach. "Although the clinical significance of LRRN4 expression in CRC has never been explored before this study, a similar prognostic significance of other members of the LRRN protein family was found in gastric cancer patients." (PMID 35440048, 2022).
ovarian carcinoma (1 paper, 2020). A malignant neoplasm originating from the surface ovarian epithelium. "It was found that TOP2A, ANXA5, and LRRN4 were associated with ovarian cancer survival prognosis." (PMID 32368301, 2020).
tumor (6 papers, 2011 to 2024). "In the growth curve analyses, tumor growth was significantly inhibited by knockdown of LRRN4, indicating the promoting role of LRRN4 in CRC xenograft tumors." (PMID 35440048, 2022). "Pathologically incomplete intestinal gland was in tumor region, and IHC analysis indicated that LRRN4 was upregulated in COAD tissues, compared to the corresponding normal tissues." (PMID 34919118, 2021). "In the heterozygous tumours, 20 genes were upregulated and only leucine rich repeat neuronal 4 (Lrnn4) downregulation was observed, whereas in the knockout tumours 28 genes were up–and 8 down–regulated." (PMID 32453735, 2020). "Furthermore, a xenograft model was utilized to explore whether LRRN4 impacts xenograft tumor growth in vivo." (PMID 35440048, 2022). "A xenograft model was utilized to investigate whether LRRN4 impacts tumor growth in vivo." (PMID 35440048, 2022). "For non-immune cell populations, we identified tumor cells (EPCAM and CLDN4), fibroblasts (COL3A1 and NNMT), and mesothelial cells (LRRN4 and WT1)." (PMID 36788228, 2023).
cancer (3 papers, 2011 to 2022). A tumor composed of atypical neoplastic, often pleomorphic cells that invade other tissues. "Several biological functions and signaling pathways were regulated by LRRN4, including proteoglycans in cancer, glutamatergic synapse, Ras, MAPK and PI3K." (PMID 35440048, 2022). "Our results showed that LRRN4 plays a functional role in promoting cell proliferation and DNA synthesis and in inhibiting apoptosis, indicating a function in cancer cells similar to other members of the LRRN family." (PMID 35440048, 2022). "Apart from the functions of LRRN4 in normal tissue and benign disease, it is also involved in cancers." (PMID 35440048, 2022). "In the case of LRRN4 and UPK3B the expression was only detected in 8 or 6 of the tested lines suggesting these markers are down-regulated or lost in cancer." (PMID 21984916, 2011). "Interestingly, crosstalk among these LRRN4-related signaling pathways (Ras, MAPK, and PI3K pathways) have been reported in cancer." (PMID 35440048, 2022). "Several signaling pathways were found to be regulated by LRRN4, including the Ras signaling pathway and the mitogen-activated protein kinase (MAPK) and phosphoinositide-3 kinase (PI3K) pathways, which are known to correlate with the malignant phenotype of cancer cells." (PMID 35440048, 2022).
cardiac diseases (1 paper, 2021). "LRRN4, as a member of LRRN family, was mainly reported in regulation of cardiac diseases, central nervous system (CNS) and the peripheral nervous system (PNS)." (PMID 34919118, 2021).
LRRN4 also shares sentences with these, for which no sentence is quoted: colorectal cancer (2 papers); chronic obstructive pulmonary disease (1); colon adenocarcinoma (1); Crohn disease (1); Insulin resistance (1); lung carcinoma (1); Obesity (1); schizophrenia (1).